TNF (tumor necrosis factor)
Diseases named in the same sentence as TNF in open-access papers (continued):
Sharing a sentence is not in itself a finding about the gene and the disease.
diabetes (continued). "In agreement with the beneficial effect of doxycycline at the vascular level, it has been found that it is capable of inhibiting the expression of TNF alpha, along with other proinflammatory cytokines, which are phenomena associated with the genesis of diabetes and atherosclerosis." (PMID 36979696, 2023). "Furthermore, metformin treatment was associated with the suppression of AGEs, ET-1, TNF-α, iNOS, dyslipidemia, as well as femoral artery ultrastructural damage that had been induced by diabetes." (PMID 36830898, 2023). "Inflammatory factors such as TNF-α and IL-1β cause β-cell injury and dysfunction in diabetes." (PMID 37817130, 2023). "Chronic inflammation and elevated levels of TNFα have been shown to be associated with diabetes." (PMID 38023728, 2023). "Although, 6 and 12 mg AX consumption for 8 weeks in diabetic patients could alleviate diabetes-associated systemic inflammatory stress by reducing TNF-α circulation." (PMID 37051124, 2023). "FSH may also be associated with diabetes through inflammatory markers, such as c-reactive protein, TNF-α, and IL-1β." (PMID 36767197, 2023). "Moreover, TNF-α has been reported to be associated with several diseases, including diabetes, cardiovascular disease, cancer, and metabolic disorders." (PMID 37798684, 2023). "On the other hand, a study found that urine levels of ∑DEHP were positively associated with tumor necrosis factor-α and negatively associated with serum adiponectin levels in subgroup of 329 Chinese adults who were diagnosed with diabetes mellitus and had higher BMI." (PMID 37198693, 2023). "Hypertension and diabetes were more common in male subjects compared to female subjects (p < 0.05).Increased physical activity both at baseline and follow up were associated with decreased BMI, WC and inflammatory markers, including crp and TNF." (PMID 37107201, 2023). "In addition, hydroxychloroquine and TNF-a inhibitors can improve glucose metabolism and reduce the risk of diabetes mellitus in patients with AS." (PMID 38173714, 2023). "However, patients with chronic inflammations such as diabetes tend to produce high amounts of TNF-α, increasing their susceptibility to septic shock, and, if infected with viruses or microbes, their symptoms tend to become serious much more easily." (PMID 37569540, 2023). "It is already described that patients can establish a chronic inflammation state under diabetic conditions, characterized by a decompensated secretion of pro-inflammatory cytokines, such as TNF-α, IL-1β and IL-6, and it is suggested as the major cause of comorbidities related to diabetes." (PMID 37122742, 2023). "On the other hand, TNF-α is a cytokine largely expressed in adipose tissue in diabetes mellitus, which may be associated with impaired insulin sensitivity in GDM." (PMID 35390031, 2022). "Indeed, targeting classical inflammatory molecules including IL-1, IL-6 and TNF have been shown to reduce the risk of diabetes and improve insulin sensitivity in some studies, although with variable effects." (PMID 35480482, 2022). "Moreover, they are also recognized as adipocytokines with fairly negative impacts on insulin signaling; the combination of TNF-α and IL-6 had an impact on progressive pancreatic β-cell loss during the progression of diabetes." (PMID 36299624, 2022). "Further, polymorphisms of the tumor necrosis factor (TNF)-α gene, located on chromosome 6p21.3, increase the risk of association of insulin-dependent diabetes mellitus (Type 1 diabetes, T1D) and autoimmune thyroid disease and the association of alopecia areata and vitiligo." (PMID 35683627, 2022). "In meta-analyses, TNF inhibitors use was associated with a significant decrease in diabetes risk." (PMID 35456202, 2022).
diabetes (continued). "Modification of the F-actin network is key to islet cell function as it mediates insulin secretion and results here suggest that DSG2 is protective with loss of DSG2 in the Beta-TC-6 cells increasing the release of TNFα, a known pathogenic and proinflammatory cytokine implicated in diabetes." (PMID 36309486, 2022). "The findings of the present study corroborate with our earlier report of OPG as a marker of CV risks in diabetes, and in addition these findings indicate that TNF-α is a potential surrogate biomarker of CV risk in hypertensive patients with T2D on oral antidiabetic drugs." (PMID 36085061, 2022). "However, the bone loss, probing depth, plaque index and levels of IL-6 and TNF-α in the PICF were statistically higher in prediabetes as compared to non-diabetes, implying that hyperglycemia induces irreversible peri-implant bone alterations." (PMID 36557041, 2022). "More importantly, resistance training can result in significant reductions in the levels of proinflammatory cytokines, such as TNF-α and IL-6, that are produced in adipose tissue independent of weight loss in obese adults and even in patients with diabetes mellitus." (PMID 35928568, 2022). "Similarly, the incidence of other stroke‐associated comorbidities such as diabetes mellitus and dementia is known to be reduced by anti‐TNF‐α and anti‐IL‐1β therapy in patients with rheumatoid arthritis and comorbid type‐2 diabetes." (PMID 35971650, 2022). "C-reactive protein (CRP) is independently associated with the occurrence of atrial fibrillation, and elevated tumor necrosis factor-α (TNF-α) and interleukin-6 (IL-6) also increase the risk of type 2 diabetes mellitus, coronary heart disease and atherosclerosis." (PMID 36361072, 2022). "However, linear regression analyses demonstrated that older age was independently associated with IL-6 levels; also, older age and diabetes were independently associated with TNF-a levels in serum." (PMID 36419783, 2022). "Recently, a systematic review and meta‐analysis found that tumor necrosis factor alpha rs1800629 polymorphism might increase the risk of developing periodontitis and diabetes concerning all genetic models, mainly in Asian subjects." (PMID 35913467, 2022). "Furthermore, it is linked with diabetes and increased concentrations of inflammatory cytokines including tumor necrosis factor-α (TNF-α) and C-reactive protein in individuals with DN." (PMID 34093722, 2021). "Experimental research show that release of pro-inflammatory cytokines such as Interleukin 1β, Interleukin 6, and TNF-α in diabetes may cause neuronal death and accelerate neurodegeneration characteristic for AD." (PMID 33918576, 2021). "TNFα is a proinflammatory cytokine that promotes protection from bacterial and viral infections but has also been associated with medical complications of pregnancy such as diabetes and preeclampsia." (PMID 34959801, 2021). "Proinflammatory cytokines including TNF-α, IL-6 and IL-1β are notable cytokines that rapidly responds to oxidative damages and they have been extensively implicated in central and peripheral inflammatory reactions in diabetes." (PMID 34733158, 2021). "Patients with comorbidities, such as diabetes, asthma, and hypertension, are at higher risk of mortality because of the excessive production of inflammatory cytokines, including IL-2R, IL-10, and TNF." (PMID 34046036, 2021). "Polymorphisms of genes encoding pro- and anti-inflammatory cytokines (TNFα-308 G/A, IFNγ +874 A/T, IL-10–1082G) may be responsible for nerve damage in neuropathy, which is a common complication of diabetes." (PMID 32751810, 2020). "TNF‐α inhibition reversed increased inflammation caused by diabetes." (PMID 32794619, 2020). "Pro-inflammatory molecules such as C-reactive protein (CRP), interleukin-6 (IL-6) and tumor-necrosis factor alpha (TNFα) are associated with major chronic conditions, including diabetes, cardiovascular diseases, and age-associated conditions such as frailty and dementia." (PMID 31426866, 2019).
diabetes (continued). "However, the fact that TNF-α was upregulated after high glucose exposure in both cell types underlines the detrimental effects of diabetes." (PMID 29853786, 2018). "It has been demonstrated that a G238A TNF-α SNP in the promoter region could be associated with diabetes, and the 238A/308G haplotype has been shown to elevate the TNF-α serum level in an Indian population." (PMID 30134857, 2018). "Pathway analysis of our proteome profile indicated that diabetes is associated with activation of inflammatory and oxidative response proteins such as TNF–α, NFκB, leptin, leptin receptors, and p38 MAPK, factors that have been shown to contribute to micro and macrovascular complications of diabetes." (PMID 29121074, 2017). "In the retina and kidneys of WT mice with diabetes, increased expression of inflammatory markers (IL-6, TNFα, IL1β) in association augmented expression of ECM proteins (collagen 1αIV, fibronectin) and NF κB-P65 were observed, compared to WT non-diabetic controls." (PMID 28301595, 2017). "High levels of TNF-α may interfere with glucose metabolism and insulin sensitivity and increase the risk of new onset diabetes." (PMID 28813433, 2017). "Wogonin has been proved to mitigate inflammation, hyperglycemia, and dyslipidemia, exerting beneficial effects on diabetes and diabetes-associated diseases with elevated adiponectin expression, decreased IL-1β, IL-6, and TNF-α production, and inhibited Th17 differentiation and NF-κB signaling." (PMID 28736524, 2017). "For example, it is generally accepted that a two-way relationship exists between periodontal disease and diabetes mellitus, and that TNF-α may mediate this association." (PMID 28934245, 2017). "The role of tumor necrosis factor (TNF; chromosome 6p21.33) in hemochromatosis-associated diabetes is unknown." (PMID 28331855, 2017). "Since AGE has been shown to induce various inflammatory responses in diabetes, we checked two representative cytokines IL-6 and tumor necrosis factor (TNF)-α, both of which are classically known to be associated with the pathogenesis of DR, in addition to IL-1β." (PMID 29170525, 2017). "It has been associated with numerous autoimmune disorders (including Sjögren’s syndrome, dermatitis herpetiformis, IgA-deficiency or insulin-dependent diabetes mellitus) possibly due to an increased transcription of TNF-α and reduced complement-mediated antigenic clearance." (PMID 26001889, 2015). "Previous studies have revealed that higher levels of inflammatory mediators, such as tumor necrosis factor alpha (TNF-α), interleukin-1β (IL-1β) and IL-6, are associated with classic diabetes complications, such as nephropathy, neuropathy, retinopathy and cardiovascular disease." (PMID 26270535, 2015). "Plasma TNF-α concentration is associated with aging and the risk of diabetes mellitus." (PMID 25871293, 2015). "For example, vascular injury may occur in diabetes directly through inflammation caused by hyperglycemia and adipocytokines such as tumor necrosis factor-α (TNF-α) as well as through inflammation caused by senescent cells." (PMID 25894557, 2015). "However, it is not clear if brain damage caused by cerebral infarctions exacerbated by diabetes is reduced by blocking TNF-α." (PMID 26665003, 2015). "Since blocking the production of TNF-α improves blood glucose concentrations, targeting TNF-α could effectively reduce expressions of the primary factors behind the complications associated with diabetes." (PMID 25009576, 2014). "Raised concentrations of TNF-α may underly much of the metabolic clustering due to diabetes mellitus." (PMID 24260344, 2013). "Several studies have shown the association between TNF-alpha and diabetic vascular damage." (PMID 24259948, 2013). "This indicates that TNF-α is causally linked to renal injury in patients with diabetes and may be used as an early biomarker for the progression of DN." (PMID 24250725, 2013).
diabetes (continued). "Additionally, work in TNF receptor I (TNF-RI)-deficient mice and TNF-RII-deficient mice showed that inhibition of TNF-α can prevent the retinal complications of diabetes." (PMID 23592916, 2013). "Previous studies have demonstrated the influence of a variety of pro-inflammatory cytokine polymorphisms, including tumor necrosis factor alpha (TNFα) (rs1800629) and interleukin 6 (IL-6) (rs1800795 and rs1800797) in the risk of central obesity, diabetes and MetS phenotypes." (PMID 23306188, 2013). "Increased IL-1β and TNF-α production has been implicated in pathogenesis of obesity and diabetes." (PMID 22454632, 2012). "Both IL-8 and TNF-α are elevated in individuals with diabetes and may be involved in its risk and development." (PMID 22336131, 2012). "Elevated tumor necrosis factor-alpha (TNF-α) levels and hyperglycemia are implicated in diabetes-associated endothelial cell dysfunction and may be causal in premature atherosclerosis." (PMID 22973260, 2012). "The combined use of serum adiponectin and TNF-α R2 as biomarkers provided added value over traditional risk factors for diabetes prediction in Chinese and could be considered as an alternative to the OGTT." (PMID 22615828, 2012). "The key words were as follows: diabetes, tumor necrosis factor and polymorphism/variant/genotype." (PMID 21494616, 2011). "It is possible that TNFα upregulation may contribute to increased apoptosis detected in other diabetes associated complications and TNFα inhibition may be a potential therapeutic option in preventing this comorbidity." (PMID 20634940, 2010). "Increases in circulating levels of CRP, TNF-α, and IL-6 have been observed in the aged population and may partly account for the increased risk of atherosclerosis, type 2 diabetes mellitus, hypertension, and other cardiovascular diseases." (PMID 21253481, 2010). "The results suggest that interleukin 8, tumor necrosis factor alpha and osteoprotegerin may be promising novel biomarkers of type 1 diabetes mellitus, and may also indicate the susceptibility profile in these individuals for the worsening of the patient’s periodontal status." (PMID 40141192, 2025). "Similarly, TNF-α-deficient mice demonstrated a reduction in vascular changes induced by diabetes." (PMID 39279894, 2024). "In addition, diabetes caused a significant (p < 0.0001) upregulation of vascular tissue levels of AGEs, ET-1, and iNOS, as well as high blood levels of glycated haemoglobin, TNF-α, and dyslipidemia." (PMID 36830898, 2023). "Functional studies show that a TNF inhibitor significantly reduces expression of other cytokines, diminishes leukocyte infiltration and bone resorption in diabetic rats, indicating that cytokine dyregulation is an essential component of diabetes-enhanced periodontal bone loss in vivo." (PMID 36304447, 2022). "We measured traditional CVD risk factors [blood pressure, Body Mass Index (BMI), diabetes, age, sex, smoking], serum markers of systemic inflammation (hsCRP, GlycA) and metabolic dysfunction (cholesterol efflux capacity), and inflammatory cytokines (IL-1β, IL-6, IL-12/IL-23, IL-17A, TNF-α, IFN-γ)." (PMID 35720288, 2022). "The values of evaluated pro-inflammatory cytokines, tumour necrosis factor-α (TNF-α), interleukin-6 (IL-6), and interleukin-1β (IL-1β), assessed from the ascending aorta were elevated by all three cardiovascular risk factors, with the highest levels induced by type 1 diabetes mellitus (up to 259%)." (PMID 35163364, 2022). "In addition, a previous study has shown that TNF-α can not only induce the occurrence of diabetes but also cause damage to vascular endothelial function, initiate the process of atherosclerosis, and increase the risk of various complications of diabetes." (PMID 36284987, 2022).
diabetes (continued). "miR-29ab1 plays a crucial role in diabetes-related macrophage inflammation, and ectopic increases in miR-29a and miR-29b1 in diabetic skin wounds are associated with upregulation of M1 polarization and IL-1β, compared with healthy subjects, as well as with elevated TNF-α levels." (PMID 36601058, 2022). "Upon exposure to diabetic stress consisting of hyperglycemia, tumor necrosis factor (TNF), and interleukin-6 (IL-6), these capillaries underwent massive thickening in the basement membrane as evidenced by collagen IV staining, a hallmark of diabetes-induced vasculopathy." (PMID 33790786, 2021). "Importantly, TNF-α specifically is associated with diabetic retinopathy, providing a basis by which diabetes and dyslipidemia could synergistically worsen DR." (PMID 33828528, 2021). "Since glucose homeostasis in diabetes can be disrupted not only by the loss of insulin-producing function and the development of β-cell dysfunction, but also by increasing the content of proinflammatory cytokines in the blood, a study of TNF-α content in experimental animals was conducted." (PMID 34572994, 2021). "Similarly, effects on glucose metabolism, insulin resistance, pancreatic β cell function and risk of diabetes are attributed to elevations in TNFα and IL-1β, whilst IL-1β antagonism reduces hyperglycaemia and improves pancreatic β cell function in patients with T2D." (PMID 32907617, 2020). "Elevated TNF-α levels have been associated with the pathophysiology of reoxygenation injury, myocarditis, cardiac allograft vasculopathy, heart failure progression, arthritis, diabetes, Crohn’s disease, and also cachexia which correlated with terminal malignancy and AIDS." (PMID 32545460, 2020). "In vitro studies have confirmed that TNF-α inhibits the proliferation and differentiation of osteoblasts, promotes the apoptosis of osteoblasts, and activates osteoclasts, effects that are very similar to the proposed mechanism of the diabetes-associated bone defects." (PMID 32903738, 2020). "For example, TNFα stimulates blood-brain barrier (BBB) disruption in patients with type 2 diabetes mellitus, which could ultimately lead to loss of the BBB transport regulation of other inflammatory signals, and exacerbate allostatic load to the HPA axis, which could also lead to its dysregulation." (PMID 31349552, 2019). "Besides, diabetes could aggravate bone loss through promoting NF-κB activation and IL-6 and TNF-α release." (PMID 30459613, 2018). "Evidences indicate that hyperglycemia increases circulating IL-6 and TNF-alpha levels, by an oxidative mechanism, and this effect is more pronounced in subjects with impaired glucose tolerance, suggesting a causal role for hyperglycemia in the immune activation of diabetes." (PMID 25922592, 2015). "Other inflammatory cytokines participating in low grade inflammation in diabetes are IL-6 and TNF- α, with a role that is mainly associated with the risk of DM complications." (PMID 25793613, 2015). "Therefore, we speculate that SPARC at the onset of diabetes may be associated with regulation of Tgfb1 as well as Tgfb1-mediated TNFα production." (PMID 26110898, 2015). "Furthermore, overproduction of TNF-α and IL-6 in pancreas could cause islet dysfunction and accelerate the progression of diabetes." (PMID 24669227, 2014). "In contrast, previous studies showed that diabetes may be associated with a lower-than-average risk of acute lung injury after intratracheal instillation of LPS, and the concentrations of TNF-α in the bronchoalveolar lavage fluid of intratracheal LPS-treated diabetic rats were markedly reduced." (PMID 23671873, 2013). "Since, polymorphic variants (C and F alleles) favor higher PAI-1 levels and also overexpress PAI-1 in response to insulin, TNFα and TGFβ; it may imply an enhanced risk of suffering various conditions, such as atherosclerosis, cancer, diabetes, wound healing failure, among other diseases." (PMID 18312663, 2008).